LRRC15 (leucine rich repeat containing 15)
Diseases named in the same sentence as LRRC15 in open-access papers (continued):
Sharing a sentence is not in itself a finding about the gene and the disease.
tumor (continued). "Collectively, these data demonstrate that LRRC15 is a bona fide marker of TGFβ-driven CAFs that does not overlap with other cells within and beyond tumours." (PMID 36171287, 2022). "Beyond the tumour, expression of both Fap and Acta2 was observed in stromal cells across multiple tissues, whereas Lrrc15 was absent." (PMID 36171287, 2022). "Analyses of LRRC15+ CAF-depleted tumours revealed that universal fibroblast-like activity was enriched but without sustained ablation, LRRC15+ myofibroblasts can replenish and re-establish their foothold in the CAF compartment." (PMID 36171287, 2022). "The TGFβ-driven population represented ~60% of all CAFs in late-stage tumours, despite being absent in normal pancreas, and was defined by expression of the leucine-rich repeat containing 15 (LRRC15) protein." (PMID 34638468, 2021). "These LRRC15+ CAFs, which clustered with myCAFs, surrounded tumor islets and were absent from normal pancreatic tissue." (PMID 32752017, 2020). "Notably, PLXDC1+TPSCs located near aggressive LRRC15+ myCAFs and SPP1+ macrophages could form a desmoplastic and immunosuppressive niche around the tumor boundary, promoting CD8 T cell exhaustion in pancreatic ductal adenoma." (PMID 41425545, 2025). "Focusing on the tumor microenvironment, single-cell analysis in PDAC identified TGFβ-driven LRRC15+ CAFs that surround tumor islets, are absent in normal tissue, and whose high signature correlates with poor anti-PD-L1 response, highlighting a translational target to improve immunotherapy outcomes." (PMID 41316282, 2025). "First, we observed a negative correlation between LRRC15 and tumour purity." (PMID 36653841, 2023). "That is, the high expression of LRRC15 is not mainly reflected in the tumour parenchyma but may promote the proliferation of HGSC stroma." (PMID 36653841, 2023). "We next asked whether the absence of LRRC15+ CAFs improved the responsiveness to anti-PDL1 treatment in KPR tumours grown in the pancreas." (PMID 36171287, 2022). "Additionally, it will be important to understand whether LRRC15+ CAFs dictate ICB responsiveness similarly across different indications and tumour immune phenotypes." (PMID 36171287, 2022). "In naive, non-tumour-bearing skin, Lrrc15 expression was absent and all cells were uniformly Pi16+." (PMID 36171287, 2022). "The study also confirmed LRRC15 could contribute to GAMs infiltration and tumour proliferation in GBM, which was consistent with previous studies that many LRR‐containing proteins are involved in tumour progression." (PMID 33960636, 2021).
infection (5 papers, 2022 to 2025). The state of being infected such as from the introduction of a foreign agent such as serum, vaccine, antigenic substance or organism. "Our analysis of public expression datasets suggests LRRC15 is expressed in tissues susceptible to infection at levels comparable to or exceeding those of ACE2." (PMID 36735681, 2023). "For authentic virus monoculture and co-culture infection assays, cell death for both control and LRRC15-transfected cells was normalized to uninfected cells of the same line." (PMID 36757924, 2023). "We then tested if LRRC15 expression impacted infection of HEK293T-ACE2 and HEK293T-ACE2-TMPRSS2 cells." (PMID 36757924, 2023). "Both TurboGFP-tagged and Myc-DDK-tagged LRRC15 constructs were used in pseudovirus infection experiments assessing cis-inhibition of infection." (PMID 36757924, 2023). "While our data highlights a new role for LRRC15 in promoting SARS-CoV-2 spike binding, limiting infection, and regulating collagen expression, it is currently unclear how LRRC15 contributes to human COVID-19 disease." (PMID 36757924, 2023). "Next, we tested if LRRC15 expression can also suppress viral replication and cytopathic effect in infection with authentic SARS-CoV-2 virus." (PMID 36757924, 2023). "More experimental investigation into the spike-LRRC15 interaction is warranted to further establish the theories about its potential role in preventing infection." (PMID 36680105, 2022). "Our own data have not detected any trans effect that LRRC15-expressing cells have on the infection of nearby susceptible target cells." (PMID 36735681, 2023). "Indeed, we found LRRC15+ fibroblasts can antagonize infection of both SARS-CoV-2 pseudovirus and authentic SARS-CoV-2 virus (Wuhan)." (PMID 36757924, 2023). "These could provide a means for further dissecting the biology of LRRC15 in infection and eventually may be possible to repurpose in patient settings." (PMID 36735681, 2023). "Next, we examined if LRRC15 is able to suppress the infection of live SARS-CoV-2." (PMID 36228039, 2022). "However, expression of LRRC15 was insufficient to make the cells permissive to infection." (PMID 36735681, 2023). "Although LRRC15 reduced the entry of pseudotyped viruses of all tested variants at a similar fold in HeLa-ACE2 cells, different binding affinity may alter the phenotype in different settings like naturally susceptible cells or infection in the lung." (PMID 36228039, 2022). "Overall, we describe the TLR-related receptor LRRC15 as a new spike receptor that can bind and sequester SARS-CoV-2 and limit infection." (PMID 36757924, 2023). "Additionally, LRRC15 expression could regulate the reaction of fibroblasts to infection." (PMID 36680105, 2022). "The role of LRRC15 is currently best explained as SARS-CoV-2-virion-sequestering, protecting nearby ACE2-positive cells from infection." (PMID 36680105, 2022). "Interestingly, leucine-rich repeat-containing protein 15 (LRRC15), which was one TLR-related cell surface receptor, was found to be a novel receptor of the spike protein of SARS-CoV-2; however, it sequesters the infection of this virus." (PMID 41011341, 2025). "We also investigated the alternative scenario where LRRC15 and ACE2 are expressed on different cells, to measure whether we could detect a trans effect on infection." (PMID 36735681, 2023). "Coculturing ACE2-expressing cells in the presence of cells overexpressing LRRC15 did not appreciably enhance nor inhibit infection of the ACE2-expressing population when using wild-type isolates of SARS-CoV-2." (PMID 36735681, 2023). "While there is agreement that LRRC15 can have an enhancing role when present on cells expressing ACE2, whether LRRC15 also has an inhibitory effect on infection in trans is one point of divergence between these studies." (PMID 36735681, 2023). "Although infection assays demonstrated that LRRC15 alone is not sufficient to permit viral entry, we present evidence that it can modulate infection of human cells." (PMID 36735681, 2023).
infection (continued). "For infection of cells with SARS-CoV-2 pseudovirus in cis inhibition assays, WT HEK293T, HEK293T-ACE2, and HEK293T-ACE2-TMPRSS2 cells were transfected with cDNA for myc-DDK-tagged LRRC15 transcript 1 or a control plasmid (lentiGuide-Puro; Addgene #52963)." (PMID 36757924, 2023). "Our data suggests the primary mechanism of action for LRRC15 in the context of SARS-CoV-2 infection is likely through a direct interaction with the spike protein that sequesters SARS-CoV-2 virions and in this way helps to limit infection." (PMID 36757924, 2023). "Ectopic expression of LRRC15 did not inhibit infection (two-way ANOVA, p = 0.378)." (PMID 36757924, 2023). "Similarly, when we tested a sequential model where virions first encounter LRRC15-expressing cells and then subsequently are exposed to ACE2-expressing cells, we likewise did not observe evidence for a strong trans effect on infection." (PMID 36735681, 2023).
LRRC15 also shares sentences with these, for which no sentence is quoted: Hypertension (2 papers); rheumatoid arthritis (2); triple-negative breast carcinoma (2); adenocarcinoma (1); adrenocortical carcinoma (1); androgenetic alopecia (1); bone cancer (1); calcific aortic valve disease (1); cholangiocarcinoma (1); colon adenocarcinoma (1); dental caries (1); hidradenitis suppurativa (1); liposarcoma (1); lung adenocarcinoma (1); lung squamous cell carcinoma (1); non-small cell lung adenocarcinoma (1); non-small cell lung carcinoma (1); rectum adenocarcinoma (1); renal cell carcinoma (1); rhabdomyosarcoma (1); skin cancer (1); type 1 diabetes (1); Umbilical hernia (1); uterine corpus endometrial carcinoma (1).